CSF1 (colony stimulating factor 1)
Diseases named in the same sentence as CSF1 in open-access papers (continued):
Sharing a sentence is not in itself a finding about the gene and the disease.
myocarditis (3 papers, 2018 to 2024). Myocarditis is a condition that is characterized by inflammation of the heart muscle (myocardium). "The overexpression of CSF-1 in myocarditis patients controls monocytes originating from hematopoietic stem cells." (PMID 39113804, 2024). "Consistent with our findings in patients, CSF-1 production was increased within inflammatory foci at the acute state of myocarditis in mice." (PMID 30349538, 2018). "Since pathogens are frequently involved in the pathogenesis of myocarditis, as a next step we set up an experimental approach to decipher the CSF-1 axis using nanoparticle-encapsulated siRNA in a mouse model of virus-mediated myocarditis." (PMID 30349538, 2018). "Our data indicate a pronounced up-regulation particularly of CSF-1 and CSF-1R in endomyocardial specimen from patients with myocarditis/inflammatory cardiomyopathy." (PMID 30349538, 2018). "Based on this, we sought to modulate the virus-triggered inflammatory response in an experimental model of Coxsackievirus B3-induced myocarditis by silencing the CSF-1 axis in myeloid cells using nanoparticle-encapsulated siRNA." (PMID 30349538, 2018). "Immunohistochemical stain of heart tissue from patients with myocarditis revealed CSF-1 expressing cells only within inflammatory foci, with a strong focus on mononuclear immune cells." (PMID 30349538, 2018). "Here, we demonstrate RNA sequencing data obtained from endomyocardial biopsies of patients with myocarditis indicating a significantly increased production of Colony Stimulating Factor 1 (CSF-1)." (PMID 30349538, 2018). "Since monocytes/macrophages represent the major infiltrating cell population in acute myocarditis, it is very likely that these cells are also involved in CSF-1 production." (PMID 30349538, 2018). "Based on this, we hypothesized that disruption of the CSF-1 axis in myeloid cells attenuates heart muscle inflammation and the resulting organ damage during myocarditis." (PMID 30349538, 2018). "First, we determined CSF-1 production in a mouse model of CVB3-induced myocarditis." (PMID 30349538, 2018). "Nevertheless, at the acute state of virus-mediated myocarditis, we observed that Mac-3 positive cells like monocytes/macrophages, which infiltrate the heart, may represent the main producers of CSF-1." (PMID 30349538, 2018). "Thus, in order to investigate the pathophysiological function of CSF-1 production by monocytes/macrophages on inflammatory tissue damage during myocarditis, we decided to use a nanoparticle-encapsulated siRNA approach to target CSF-1 production in myeloid cells." (PMID 30349538, 2018).
nephritis (3 papers, 2017 to 2021). Inflammation of renal tissue. "CD44 is a glycoprotein that is expressed on immune cells, whereas CSF-1 is a growth factor for macrophages; and both of these genes are upregulated in nephritis." (PMID 31817608, 2019).
neuropathy (3 papers, 2016 to 2023). A disorder affecting the nervous system that manifests with pain, tingling, numbness, and/or muscle weakness. "Another direction for an immune‐modulatory treatment approach might emerge by interfering with the CSF‐1‐CSF‐1R axis, based on the robust and persistent amelioration of neuropathy by CSF‐1 deficiency in different CMT1 mouse models." (PMID 26250643, 2016). "In particular, an important infiltration of pro-inflammatory CD4+ lymphocytes occurs in the leptomeninges of the dorsal root ganglia in neuropathic pain model or in spinal meninges in CSF1 neuropathy-mimicking model, which may interact with microglia to modulate mechanical hypersensitivity." (PMID 37860691, 2023).
steatosis (3 papers, 2018 to 2022). Increased lipid within the cytoplasm of cells. "Instead, neonatal rats treated with CSF1 displayed reversible hepatic steatosis and Kupffer cell expansion." (PMID 29351395, 2018). "The coordinated reduction of numerous genes involved in lipid metabolism in the liver in 3 wk old Csf1rko rats is the reciprocal of the increase observed following CSF1 treatment of neonates and likely contributes to both the progressive steatosis and the lack of visceral adipose in the animals." (PMID 34081701, 2021). "The plasma levels of CX3CL1, TNF, CD40, CSF‐1, and TWEAK were lower in moderate steatosis versus no steatosis." (PMID 35128832, 2022).
ulcerative colitis (3 papers, 2019 to 2025). An inflammatory bowel disease involving the mucosal surface of the large intestine and rectum. "CSF1 and IL34 are also both induced after epithelial injury in the intestine, including in human ulcerative colitis." (PMID 40533345, 2025).
autoimmune myocarditis (2 papers, 2018 to 2023). Autoimmune myocarditis is an autoimmune disease that affects the heart. "Taken together, modulation of the CSF-1 axis in the myeloid cell lineage with siRNAs at early stages has beneficial acute and long-term effects in both viral and autoimmune myocarditis." (PMID 30349538, 2018). "CSF-1 is responsible for the differentiation and maturation of monocytes that are involved in the inflammatory response-which induces cardiac damage during viral and autoimmune myocarditis." (PMID 37019881, 2023). "In conclusion, during viral and autoimmune myocarditis silencing of the myeloid CSF-1 axis by nanoparticle-encapsulated siRNA is beneficial for preventing inflammatory tissue damage in the heart and preserving cardiac function without compromising innate immunity's critical defense mechanisms." (PMID 30349538, 2018).
bladder tumor (2 papers, 2014 to 2021). "Even if CSF1 was secreted by bladder tumor cells, only 34% of patients have a high expression of CSF1 in tumor tissues." (PMID 34572939, 2021).
bone giant cell tumor (2 papers, 2019 to 2022). A benign but locally aggressive tumor that arises from the bone and is composed of mononuclear cells admixed with macrophages and osteoclast-like giant cells. "Conversely, no CSF1 expression was observed in any case of giant cell tumor of bone, aneurysmal bone cyst, or giant cell reparative granuloma." (PMID 36320082, 2022). "On the other hand, no cases of giant cell tumor of bone, aneurysmal bone cyst, or giant cell reparative granuloma exhibited CSF1 expression." (PMID 36320082, 2022).
bone metastasis (2 papers, 2022 to 2025). Transfer of a neoplasm from its primary site to bones. "A panel of cytokines including interleukin 1 (IL1), interleukin 6 (IL6), parathyroid hormone like hormone (PTHrP) and colony-stimulating factor 1 (CSF-1) can induce the activation of osteoclasts in bone metastasis." (PMID 35685372, 2022). "Six proteins (CSF-1, CCL4, CCL3, CD83, IL-12, and CD244) and three clinical characteristics (LDH levels, bone metastasis status, and liver metastasis status) were incorporated into the predictive model." (PMID 40404633, 2025).
Brain atrophy (2 papers, 2020 to 2025). Partial or complete wasting (loss) of brain tissue that was once present. "Rh-CSF1 significantly improved the neurological deficits at 48 h and 4 weeks after HI, which was accompanied by a reduction in the brain infarct area, brain edema, brain atrophy, and neuroinflammation." (PMID 32522286, 2020). "Thus, while T2LL-dysproportional brain atrophy and SC injury share proteomic signatures, pwMS with disproportional SC injury have additional CSF proteomic changes suggestive of sustained ICs formation and disrupted IL34/CSF1 signaling axis." (PMID 41339376, 2025).
brain injury (2 papers, 2020 to 2023). Acute and chronic (see also brain INJURIES, CHRONIC) injuries to the brain, including the cerebral hemispheres, CEREBELLUM, and brain STEM. "Moreover, the expressions of CSF1 and CSF1R in neurons profoundly increased after a variety of brain injuries." (PMID 33101590, 2020).
Cerebral ischemia (2 papers, 2019 to 2025). Restriction of arterial blood supply to the brain associated with insufficient oxygenation to support the metabolic requirements of the tissue. "Similarly, previous studies have demonstrated that the proliferation of microglia is impaired in the Csf1-/- mice after cerebral ischemia, facial nerve axotomy, and intrahippocampal injection of kinate." (PMID 31906095, 2019).
cholangiocarcinoma (2 papers, 2023). A carcinoma that arises from the intrahepatic biliary tree (intrahepatic cholangiocarcinoma) or from the junction, or adjacent to the junction, of the right and left hepatic ducts (hilar cholangiocarcinoma). "TRAIL and CSF1 were prognostic factors in intrahepatic cholangiocarcinoma." (PMID 37404757, 2023).
Chronic colitis (2 papers, 2016 to 2017). A chronic inflammatory disease of the large intestine (colon, cecum and rectum). "Levels of the inflammatory cytokinesTNF-α, IL-1β, IL-6, MCP-1, and CSF-1 and of COX-2 were measured in mice with chronic colitis." (PMID 29245972, 2017). "Colorectal mRNA levels of inflammatory cytokines TNF-α, IL-1β, IL-6, MCP-1, and CSF-1, and COX-2, were measured in mice with chronic colitis." (PMID 27557503, 2016).
chronic granulomatous disease (2 papers, 2023). Chronic granulomatous disease (CGD) is a rare primary immunodeficiency, mainly affecting phagocytes, which is characterized by an increased susceptibility to severe and recurrent bacterial and fungal infections, along with the development of granulomas. "Monocyte response to CSF-1 is altered in patients with a chronic granulomatous disease, which are constitutively defective in NOX2." (PMID 36835566, 2023).
chronic obstructive pulmonary disease (2 papers, 2021 to 2023). A chronic and progressive lung disorder characterized by the loss of elasticity of the bronchial tree and the air sacs, destruction of the air sacs wall, thickening of the bronchial wall, and mucous accumulation in the bronchial tree. "XFPC may regulate autophagy by down-regulating the expression of CSF1, MAPK9, MAP3K7, and AKT3, thus achieving the purpose of treating chronic obstructive pulmonary disease." (PMID 37274101, 2023).
diabetic neuropathy (2 papers, 2022 to 2025). A chronic, pathological complication associated with diabetes mellitus, where nerve damages are incurred due to diabetic microvascular injury involving small blood vessels that supply these nerves, resulting in peripheral and/or autonomic nerve dysfunction. "There are indications that CD40 as well as CSF-1 is elevated in painful diabetic neuropathy." (PMID 41272580, 2025).
Eosinophilia (2 papers, 2020 to 2023). "CSF1 over‐expression is the most likely cause of the marked Langerhans cell reaction, leading to subsequent eosinophilia and sclerosis." (PMID 37305870, 2023).
hearing loss (2 papers, 2019 to 2023). "As a TF, FOS may participate in inflammation by regulating its target genes, such as ICAM-1, CSF1 and CCL5 which were all important inflammatory proteins for hearing loss." (PMID 31149396, 2019).
heart failure (2 papers, 2019 to 2024). Inability of the heart to pump blood at an adequate rate to meet tissue metabolic requirements. "It included proteins like NT-proBNP (NPPB), growth differentiation factor 15 (GDF15), and fibroblast growth factor 23 (FGF23), markers that are known to be tightly related to heart failure and further systemic diseases, but also inflammatory proteins (CXCL8, CSF1)." (PMID 38999939, 2024).
Hepatitis (2 papers, 2008 to 2024). Inflammation of the liver. "We identified 7 proteins that significantly differentiate HCC patients from hepatitis patients (p < 0.05) (AFP, CTNNB, CSF1, SELL, IGFBP6, IL6R, and VCAM1)." (PMID 19578489, 2008).
infarction (2 papers, 2015 to 2022). A localised pathological necrosis of tissue resulting from obstruction of the blood supply usually by a thrombus, an embolus, or vascular torsion. "Clinical realization of CSF-1 or its analogues as a therapeutic in cardioprotection may however require a more sophisticated delivery approach, localized to the area of infarction and sustained throughout the recovery phase." (PMID 26407006, 2015).
inflammatory breast carcinoma (2 papers, 2018 to 2020). An advanced, invasive breast adenocarcinoma characterized by the presence of distinct changes in the overlying skin. "In inflammatory breast cancer (IBC) cells, the colony stimulating factor (CSF)-1/ receptor tyrosine kinase of CSF-1 (CSF-1R) axis has a functional role in hybrid E/M phenotype development and metastasis." (PMID 33207810, 2020).
invasive ductal carcinoma (2 papers, 2014 to 2017). "Moreover, several studies have shown a positive correlation between the number of infiltrating macrophages in invasive ductal carcinoma and the expression of CCL2, CSF-1, and CCL5." (PMID 28881599, 2017).
joint disease (2 papers, 2017). "Furthermore, these results showed increased CSF-1 levels in patients reporting muscle and joint diseases." (PMID 28779164, 2017). "Our result thus suggests that assessment of CSF-1 levels in saliva might be valuable for monitoring patients with muscle and joint diseases and tumors however, further investigations are needed." (PMID 28779164, 2017). "Individuals having muscle and joint diseases (n = 96) showed increased levels of CSF-1 as compared to patients not having the disease (n = 335), but the difference was lost after CSF-1 correction for total amount of protein." (PMID 28779164, 2017). "Participants with muscle and joint disease exhibited increased CSF-1 levels as compared to those without." (PMID 28779164, 2017).
kidney cancer (2 papers, 2019 to 2022). Primary or metastatic malignant neoplasm involving the kidney. "CSF‐1 (colony‐stimulating factor‐1) is disproportionate in different cancers including breast, cervical, endometrial, and kidney cancers." (PMID 35441741, 2022). "CSF1 and IL34 are expressed in various tumors (TCGA database) such as kidney cancers." (PMID 31552020, 2019).
latent infection (2 papers, 2019 to 2021). "Our previous work showed that injection of IFNγ DNA into wild-type (WT) mice increased primary and latent infection in latently infected mice, while injection of CSF-1 DNA reduced primary and latent infection in these mice." (PMID 34653236, 2021). "We previously reported that HSV-1 infected mice, with macrophages altered toward the M2 phenotype by colony stimulating factor-1 (CSF-1) injection, showed less primary and latent infection than mice with macrophages altered toward the M1 phenotype by IFN-γ injection." (PMID 30998796, 2019).
leukocytosis (2 papers, 2015 to 2020). "CSF1 treatment caused a leukocytosis, with a two- to three-fold increase in total white cell count in all treated birds (not shown)." (PMID 25857347, 2015).
malignant meningiomas (2 papers, 2021 to 2022). "Intervention with an anti-CSF1/CSF1R antibody was found to normalize the tumor microenvironment, indicating that targeting the CSF1/CSF1R axis might be a potential treatment for malignant meningiomas." (PMID 35712491, 2022).
monocytopenia (2 papers, 2012 to 2022). "Administration of colony-stimulating factor 1 in mice with hypoxic lung injury rescued the monocytopenia, altered the phenotype of circulating monocytes, increased monocyte-derived macrophages in the lung and limited injury." (PMID 35624205, 2022).
myelogenous leukemia (2 papers, 2012 to 2019). "We also conducted a cellular phosphorylation assay of CSF-1R and the downstream signaling molecules Erk and Akt using a CSF-1-dependent murine myelogenous leukemia cell line (M-NFS-60) and CSF-1-differentiated mouse BMDMs treated with 3D185 or PLX3397." (PMID 31438996, 2019).
oral cancer (2 papers, 2021 to 2025). "Moreover, in oral cancer, CSF-1 co-expresses with the transcriptional activator TWIST1 of epithelial-mesenchymal transition (EMT), accompanied by TAM infiltration, suggesting that CSF-1 induces TAM chemotaxis through CSFR activation, enhancing OSCC’s epithelial-mesenchymal transition and invasion." (PMID 40948759, 2025).
pancreatic neuroendocrine cancer (2 papers, 2013 to 2023). "CSF-1/CSF-1R and CCL2 (MCP-1)/CCR2 signaling in murine breast and pancreatic neuroendocrine cancers induces TAM recruitment and a pro-tumorigenic M2-like phenotype." (PMID 23372702, 2013).
polyp (2 papers, 2013 to 2018). A usually exophytic mass attached to the underlying tissue by a broad base or a thin stalk. "Here, we compared the levels of CSF1 in the colon LP and colon adenomas and detected a progressive increase in the amounts of CSF1 as a function of polyp size." (PMID 29422500, 2018). "In mutant APC intestinal polyposis models, CSF-1-dependent TAMs promote polyp growth." (PMID 23372702, 2013).
prostate adenocarcinoma (2 papers, 2019 to 2022). "The expression of CSF1 and all 3 NOS isoforms (NOS3, NOS2, and NOS1) were evaluated using RNA sequencing data for Prostate adenocarcinoma from The Cancer Genome Atlas (TCGA)." (PMID 36209194, 2022).
psychosis (2 papers, 2024 to 2026). "In the same week, occurrence of psychosis was associated positively with Macrophage colony-stimulating factor 1 (adjusted P value 0.040)." (PMID 39355377, 2024).
serous ovarian cancer (2 papers, 2022). "The CSF1 enhancer is highly active in the high-grade serous ovarian cancer cell line OVCAR3." (PMID 35406623, 2022).
skin cancer (2 papers, 2022 to 2024). "For example, CSF1 expression was positively correlated with the abundance of CSF1R+ CD163+ macrophages in skin cancer patients, which is consistent with a role for CSF1 in mediating macrophage survival." (PMID 39416792, 2024). "Our detection of CSF1R and CSF1/IL34 interaction between cancer and immune infiltrating cells at the epidermal layers was consistent to the biological context of the skin cancer." (PMID 35967449, 2022).
abdominal aortic aneurysm (1 paper, 2020). Enlargement and ballooning of the vessel that supplies arterial blood to the abdomen, pelvis and legs. "In a model of CaCl2 induced abdominal aortic aneurysm, BRG1 mediates TNF-α induced transcription of colony stimulating factor (CSF1) in endothelial cells to stimulate macrophage trafficking." (PMID 32733885, 2020).
acute GVHD (1 paper, 2013). "Many approaches have been developed and are being under investigation to prevent and treat acute GVHD using experimental models, including IL-21 blockade, Histone deacetylase inhibitors inducible costimulator, CSF-1, glycogen synthase kinase 3 inhibotion, Human CD8+ Regulatory T Cells." (PMID 23802653, 2013).
allergic asthma (1 paper, 2021). A asthma with a basis in a pathological type I hypersensitivity reaction. "In addition, BALF from allergic asthma patients who were challenged with airborne allergens contain increased levels of colony-stimulating factor 1 (CSF1)." (PMID 34248677, 2021).
asthenia (1 paper, 2022). Clinical sign or symptom manifested as debility, or lack or loss of strength and energy. "When combining the anti-CSF1 antibody lacnotuzumab with spartalizumab, grade ≥ 3 AEs increased, such as elevated aspartate aminotransferase (12%), asthenia (10%), and hyponatremia (10%)." (PMID 35139879, 2022).
brain infarct (1 paper, 2020). "Our results showed that the intranasal rh-CSF1 at a dose of 80 μg/kg reduced cerebral infarction area, brain edema, negative geotaxis reflex time, and alleviated body weight loss effectively, accompanied by an increase CSF1 positive microglia, and attenuation of neuroinflammation at 48 h after HI." (PMID 32522286, 2020).
chronic kidney disease (1 paper, 2023). Impairment of the renal function secondary to chronic kidney damage persisting for three or more months. "CSF1 and IL6 were previously found to be associated with kidney function and chronic kidney disease (CKD)." (PMID 37691946, 2023).
chronic lymphocytic leukemia (1 paper, 2023). "Considering the CSF1/CSF1R signaling pathway as an effective therapeutic target for depleting and reprogramming TAMs, blockade of CSF1/CSF1R signaling has been demonstrated to effectively deplete neural-like cells and control the progression of chronic lymphocytic leukemia." (PMID 36845095, 2023).